TLR4 (toll like receptor 4)
Diseases named in the same sentence as TLR4 in open-access papers (continued):
Sharing a sentence is not in itself a finding about the gene and the disease.
ischemic stroke (continued). "CKN alleviates ischemic stroke injury via LXRα/ABCA1 activation and TLR4 inhibition." (PMID 40880849, 2025). "Similarly, in ischemic stroke, NEAT1 promotes ferroptosis by acting as a ceRNA, sponging miR-17-5p, and enhancing TLR4 expression." (PMID 41268533, 2025). "Following ischaemic stroke, VNS can inhibit Toll-like receptor 4/NF-κB expression." (PMID 37153558, 2023). "Thus, targeting the TLR4/NF-κB/MAPK signal pathway and its mediated inflammation is a potential therapeutic direction against ischaemic stroke." (PMID 34196587, 2021). "Microglial GPR30 exerts acute neuroprotective effects by inhibiting TLR4-mediated microglial inflammation, which indicates that GPR30 may be a potential target for the treatment of ischemic stroke." (PMID 30001721, 2018). "Therefore, identifying the specific Prx(s) that activate TLR4 may promote the development of novel aseptic neuroinflammation models in vitro and innovative approaches with a prolonged time window for the treatment of neuroinflammation and brain injury after ischemic stroke." (PMID 27716839, 2016). "Taken together, this suggests that TLR4 signalling could be an additional player in the pro-inflammatory reactions that exacerbate disease progression in ALS in ischemic stroke and Alzheimer’s disease." (PMID 25962427, 2015). "These TLR4-independent mechanisms represent an emerging area of interest in neuroprotection, especially in conditions like ischemic stroke and traumatic brain injury, where TLR4 activation might not be the sole contributor to damage." (PMID 40723833, 2025). "The antitumor activity and acute myeloid leukocyte drug methylisoindigo attenuated ischemic stroke-induced brain injury by blocking the activation of NLRP3 inflammatory vesicles and modulating microglia/macrophage polarization through inhibition of the TLR4/NF-κB signaling pathway." (PMID 38740617, 2025). "Mechanistically, the anti-neuroinflammatory effects of SAD in ischemic stroke may be attributed to its inhibitory action on high mobility group box 1 (HMGB1) nuclear-to-cytoplasmic translocation and subsequent blockade of the TLR4/MyD88/NF-κB signaling cascade activation." (PMID 40756985, 2025). "Moreover, LPS, which is a TLR4 agonist, counteracted the impacts of TEAS, indicating that the TLR4/MyD88/NF-κB pathway exerts vital effects on the defensive mechanisms of TEAS against ischemic stroke." (PMID 38273974, 2023). "TLR4 and C5aR1 contributed to inflammation and apoptosis via activating cAMP/PKA/I-κB/NF-κB signaling during cerebral I/R, suggesting that this signaling pathway may be a potent therapeutic target in ischemic stroke." (PMID 33633530, 2021). "Taken together, these findings indicate that CSO treatment inhibited TLR4-mediated microglial activation and TNF-α secretion, thereby inhibiting NF-κB-mediated A1 astrocyte activation and reducing C3d expression and secretion, ultimately alleviating neuronal damage induced by ischemic stroke injury." (PMID 32917229, 2020). "Thus, microglial GPR30 exerts neuroprotective effects against cerebral ischemic injury by inhibiting TLR4-mediated microglial inflammation, suggesting that GPR30 may be a potential therapeutic target in the treatment of ischemic stroke." (PMID 30001721, 2018). "In conclusion, Danshensu and HSYA individually has significant therapeutic effects on ischemic stroke but Danshensu and HSYA in combination appeared to possessed additive or synergistic protective effects, which may relate to the better regulation on TLR4/NF-κb and Nrf2/HO-1 pathways." (PMID 29383171, 2017). "Therefore, we investigated if and by which route (i. a., i. v., i. p.)pharmacological in vivo-TLR4-inhibition after ischemic stroke would protect against ischemic brain injury without the detrimental long-term effects observed in TLR2-deficient mice." (PMID 26849209, 2016).
ischemic stroke (continued). "In addition, there is evidence indicating that HMGB1-toll-like receptor 4 (TLR4) signaling participates in neuronal cell death and glutamate neurotoxicity; however, its role in astrocytic dysfunction during ischemic stroke has not been reported before." (PMID 33287126, 2020).
lung cancer (131 papers, 2010 to 2025). A malignant neoplasm involving the lung. "(2020) reported a positive correlation between TLR4 and PD‐L1 expression, with higher levels linked to worse prognosis in non‐small cell lung cancer." (PMID 40762187, 2025). "It has been discovered that TLR4 signaling via NF-κB in TAM is also associated with Tumor metastasis suppression in mouse lung cancer models." (PMID 36419877, 2022). "High expression level of TLR4 was significantly associated with good survival in lung cancer (P=0.028)." (PMID 34660305, 2021). "Researchers didn’t find that TLR4 rs11536891 was associated with the risk of prostate cancer and lung cancer." (PMID 33585082, 2021). "Using a 3-D model of tumor-associated extracellular matrix, we demonstrate that lung cancer cells seeded onto this matrix activate a TLR4/NF-κB signaling pathway leading to a robust increase in the release of IL-8." (PMID 32231714, 2020). "In the gender and age stratification analysis, we found that at least one TLR4 rs7869402T allele in the male and low-age groups had a reduced risk of lung cancer." (PMID 32351566, 2020). "In the present study, we assayed the expression level and association of TLR4 and PD-L1 in lung cancer tissues and evaluated the predicting role of TLR4 in cancer cells on postoperative survival in NSCLC patients receiving pulmonary lobectomy." (PMID 28484456, 2017). "Studies in human populations demonstrated that the TLR4 polymorphism that confers reduced TLR activity (rs4986790) was also associated with elevated lung cancer risk." (PMID 29190881, 2017). "Recent research has shown that TLR4-deficient mice have a higher incidence of lung cancer than normal mice, suggesting that TLR4 has a preventive role in genesis of tumors." (PMID 22087162, 2011). "TLR4 expression was associated with poor prognosis in patients with nonsmall cell lung cancer." (PMID 37689745, 2023). "In addition, the activation of TLR2, TLR3, and TLR4 was functionally implicated in lung cancer proliferation, migration, and invasion." (PMID 37287005, 2023). "Taken together, we conclude that expression of TLR4 in lung cancer is associated with PD-L1 and could predict the outcome of patients with NSCLC receiving pulmonary resection for cancer." (PMID 28484456, 2017). "In addition, the antimicrobial peptide LL-37 created from myeloid cells fortifies the arrangement of lung cancer by causing glycogen synthase kinase 3β actuation and protein kinase B, which are interceded by TLR4 in lung tumor cells and actuate Wnt/β -linked protein signaling." (PMID 40727443, 2025). "Therefore, TLR4 may become a susceptibility biomarker for early screening of lung cancer and improve the survival rate of lung cancer patients." (PMID 32351566, 2020). "In radiotherapy, HMGB1 both activates anti-tumor immunity and aids DNA repair, interacting with Ku70 in nasopharyngeal carcinoma and modulating the TLR4/NF-κB axis in lung cancer." (PMID 40969278, 2025). "It was reported that TLR4 is a functional receptor of resistin in lung cancer cell migration and invasion." (PMID 40860289, 2025). "Considering the elevated expression of TLR4 in lung cancer and its role in cancer cell proliferation, we investigated the impact of TLR4 inhibition on the proliferation of NSCLC cell lines." (PMID 41332426, 2025). "High expression of TLR4 was detected in a majority of lung cancer specimens (mainly NSCLC) compared to tumor-free lung tissue, with TLR4 expression levels positively linked to tumor cell differentiation." (PMID 39238498, 2024). "Activation of TLR4 by LPS has been shown to induce resistance of lung cancer cells to TNFα or TRAIL-induced apoptosis through NF-κB upregulation." (PMID 37112730, 2023). "Given our results, it was revealed that even in vivo model, the activation of TLR4 played a key role in preventing lung cancer progression, in consistent with our bioinformation analysis deprived from TCGA and GEO profiles." (PMID 37553698, 2023).
lung cancer (continued). "TLR4 signaling was shown to promote immune escape of human lung cancer cells by inducing immunosuppressive cytokines and apoptosis resistance." (PMID 37112730, 2023). "Studies have found that TLR4 expression was positively correlated with tumor differentiation in lung cancer patients, and patients with TLR4 overexpression had a poorer prognosis." (PMID 37714937, 2023). "Then, relative animal experiments were performed in vivo, with results of that the stimulation of TLR4 suppressed the growth of lung cancer." (PMID 37553698, 2023). "SRC promotes lung cancer cell invasion and metastasis through the activation of each TLR4-NF-κB pathway." (PMID 37763758, 2023). "Nanoparticles can also downregulate the expression of Toll-like receptor 4, which is known as carcinogenesis in lung cancer cells and affects lung cancer treatment." (PMID 37538179, 2023). "Other TLR4 agonists like monophosphoryl lipid-A trigger the activation of TLR4 and are used as a therapeutic agent against lung carcinoma." (PMID 37822929, 2023). "Previously studies reported that PSP can exert an immunoenhancement effect against lung cancer through inhibiting the TLR4-MAPK/NF-κB signaling pathways." (PMID 35845572, 2022). "Recent studies have shown that the TRAF6-BECN1 signaling axis plays a key role in the induction of autophagy, thereby promoting lung cancer migration and invasion in response to TLR4 stimulation." (PMID 35422093, 2022). "TNF receptor-associated factor 6 (TRAF6)-BECN1 signaling axis plays a pivotal role in autophagy induction through ubiquitination of BECN1, thereby inducing lung cancer migration and invasion in response to toll-like receptor 4 (TLR4) stimulation." (PMID 35422093, 2022). "USP15KO lung cancer cells exhibited increased cancer migration and invasion induced by TLR4 stimulation through the regulation of autophagy." (PMID 35422093, 2022). "In support of this, the TCGA-based analysis revealed that the levels of human macrophage marker CD68 and TLR4 were negatively correlated with the overall survival of patients with lung cancer." (PMID 36542153, 2022). "A study showed that TLR4 induced by LPS promoted the secretion of immunosuppressive cytokines which promoted the proliferation of lung cancer and ESCC cells." (PMID 33585082, 2021). "TLR4 is notorious for its fundamental participation in the pathogenesis of human lung cancer, neuroblastoma, colorectal cancer and thyroid carcinomas." (PMID 33336901, 2021). "After cultured in CAF-CM, the TLR4 expression in lung cancer cells increased, followed by the enhancement of IκBα phosphorylation as well as p65 phosphorylation, meanwhile, total IκBα and p65 remained unchanged." (PMID 34552063, 2021). "The significance of TLR4 in disease progression was shown also in human lung cancers, as well as ovarian cancer." (PMID 33669782, 2021). "The silencing of TLR4 by siRNA can promote apoptosis and metastasize and inhibit lung cancer cell growth." (PMID 32351566, 2020). "As a lung cancer cell sensor, TLR4 regulate lung cancer progression in terms of cell growth, invasion, angiogenesis, and tumor stem cell behavior." (PMID 32445554, 2020). "For example, activation of TLR2 or TLR4 signals on TAMs increases the lung cancer metastasis via TNF-α and IL-6 production." (PMID 32788720, 2020). "TLR4-induced autophagy activation promoted migration and invasion of lung cancer by induction of chemokines and immunosuppressive factors, such as IL-6, MMP2, and CCL2." (PMID 33172060, 2020). "This is in contrast with previous studies using higher doses showing, e.g., that NiCl2 promotes the invasive potential of lung cancer cells via the activation of TLR4 signaling following acute exposures." (PMID 32244462, 2020). "In a lung cancer model, TLR4 and TLR3 activation caused an induction of autophagy, which enhanced cytokine production and increased the migration and invasion of lung cancer cells." (PMID 32745353, 2020).
lung cancer (continued). "In conclusion, our results provided new evidence that TLR4 contributed to the progress of lung cancer." (PMID 32351566, 2020). "It has been previously reported that TLR4-induced autophagy activation promoted migration and invasion of lung cancer by induction of chemokines and immunosuppressive factors including CCL2, CCL20, IL-6, VEGFA, and MMP2." (PMID 32384667, 2020). "Studies have shown that TLR4 is overexpressed in lung cancer tissues, and the knockdown of TLR4 can promote apoptosis of A549 cells and inhibit the growth of tumor cells." (PMID 32351566, 2020). "TLR4 is a complicated pathway; in acute lung inflammation/injury models, TLR4 is typically pro-inflammatory, whereas in lung cancer, appears to be protective." (PMID 31018556, 2019). "Studies found that nickel compounds (eg. nickel chloride) significantly activated TGF-β signaling pathway by TLR4/MyD88 and NF-κB signaling pathway, and further enhance the invasive ability of lung cancer tumor cells." (PMID 30621196, 2019). "Galectin-3 activates TLR4 signaling thus affecting lung cancer cell proliferation and migration through TLR4/NF-κB/NEAT1." (PMID 29788922, 2018). "As we have demonstrated, TLR4/NF-κB/NEAT1 can be activated by LPS stimulation; are there any other dysregulated factors in lung cancer that can modulate this TLR4/NF-κB/NEAT1 axis?" (PMID 29788922, 2018). "In contrast, TNF-α secretion by unstimulated PBMCs was lower in lung cancer than controls, while maintaining inducibility status via the TLR4/LPS pathway." (PMID 30365491, 2018). "Other studies reported that levels of TLR4 were strongly expressed in lung cancer tissue and had a positive correlation with the malignancy of lung cancer." (PMID 28484456, 2017). "Among the TLRs, TLR2 signaling can promote lung cancer cell growth and lead to reinforced invasiveness and metastasis, and TLR4 signaling can mediate metastasis via enhancing tumor cell invasion, proliferation, and survival of prostate cancer cells." (PMID 28076322, 2017). "It was verified that TLR4 also expresses in many type of tumors, such as hepatocarcinoma, glioblastoma, lung cancer and breast tumor." (PMID 29029545, 2017). "In 2015, tumor-derived MSCs from acute myeloid leukemia and lung cancer tissues and cells cultured in conditioned media from HeLa cells were reported to present a higher expression of TLR4 compared to unsorted MSCs." (PMID 29181035, 2017). "What is more, cancer expressed TLR4 was inversely correlated with serum sTLR4 level and was positively correlated with PD-L1 expression in lung cancer tissues." (PMID 28484456, 2017). "In the present study, we further proved the predicting role of lung cancer cell expressed TLR4 and observed an inverse correlation with serum sTLR4 level in patients with TNM stage I and II NSCLC." (PMID 28484456, 2017). "The current study reveals that TLR4 is a central mediator of muscle catabolism in a mouse lung cancer model in vitro and in vivo due to its coordinate activation of the UPP and the ALP." (PMID 28536426, 2017). "For lung cancer, previous research showed that TLR4 were more strongly expressed in lung cancer tissue than para-cancer tissue and was positively correlated with the differentiation degree of tumor cells." (PMID 28484456, 2017). "The TLR4 can induce the activation of NF-κB pathway which is conferred the enhanced invasion of lung cancer cells induced by nickel." (PMID 29127306, 2017). "Taken together, we proved that TLR4 was strongly expressed in lung cancer tissues and predicted poor prognosis of patients with NSCLC." (PMID 28484456, 2017). "MSCs isolated from acute myeloid leukemia and lung cancer tissues or cultured in the presence of conditioned media from HeLa cells showed an increase in TLR4 expression compared to naive MSCs." (PMID 29181035, 2017).
lung cancer (continued). "The close correlation of TLR4 expression with miR-21 and ROS levels in freshly isolated, untreated human lung cancer cells suggested a TLR4/ROS/miR-21 pathway through which Gram-negative bacteria facilitates lung cancer progression in clinical patients." (PMID 27286259, 2016). "NADPH oxidase 1-dependent ROS was crucial for TLR4 signaling triggered tumor metastasis of human lung cancer." (PMID 27286259, 2016). "Knockdown of TLR4 abrogated the increased miR-21 expression by LPS in primary human lung cancer cells." (PMID 27286259, 2016). "TLR4 activation by LPS in primary human lung cancer cells resulted in increased ROS production, which in turn induced up-regulation of miR-21 and led to tumor outgrowth." (PMID 27286259, 2016). "We demonstrate an essential role of TLR4/ROS/miR-21 pathway in LPS-induced primary human lung cancer outgrowth." (PMID 27286259, 2016). "Here we determined that TLR4 activation with LPS promoted outgrowth of primary human lung cancer cells in vitro and in vivo." (PMID 27286259, 2016). "In essence, these results demonstrate an enhanced outgrowth of primary human lung cancer by LPS trigged TLR4 signaling." (PMID 27286259, 2016). "Herein, we demonstrated that LPS promoted tumor outgrowth of primary human lung cancer though TLR4 signaling." (PMID 27286259, 2016). "Further, freshly isolated, untreated human lung cancer cells were assayed for expressions of TLR4, miR-21 and ROS levels." (PMID 27286259, 2016). "Activation of TLR4 with LPS resulted in elevated ROS production in primary human lung cancer cells, which increased miR-21 expression and tumor outgrowth." (PMID 27286259, 2016). "Activation of Toll-like receptor 4 (TLR4) signaling in human lung cancer with lipopolysaccharide (LPS) enhances tumor progression." (PMID 27286259, 2016). "For in vivo relevance, expression of TLR4 was correlated with miR-21 expression and ROS production in freshly isolated, untreated primary human lung cancer cells." (PMID 27286259, 2016). "In addition, we found in the literature that the expression levels of TLR4 /MyD88 /NF-κB were significantly upregulated in clinical lung cancer samples." (PMID 39735680, 2025). "Recent studies have demonstrated that saponins extracted from PJR inhibit tumor growth in rat models of lung cancer by modulating the TLR4/NF-κB signaling pathway and suppress the proliferation, migration, and invasion of lung cancer cells via regulation of the PTEN-PI3K-AKT signaling pathway." (PMID 41465428, 2025). "Notably, silent information regulator 2 (SIRT2) is secreted by macrophages upon TLR2 or TLR4 activation, further promoting the metastatic process of lung cancer." (PMID 40166469, 2025). "While TLR4‐PD‐L1 correlations have been studied in lymphomas and lung cancers, their role in OSCC remains unclear." (PMID 40762187, 2025). "This suggests TLR4 may have a dual function in lung cancer, one promoting tumor cell survival, and the other promoting immune defense against malignant transformation." (PMID 39238498, 2024). "Activation of TLR4 is known to promote survival in lung cancer cells via the PI3K/Akt pathway." (PMID 37233477, 2023). "Numerous studies involving TLR4 in cancer have focused on lung cancer." (PMID 37112730, 2023). "Moreover, the extracellular matrix remodeling and EGFR-mediated signaling axes induced by TLR2 and TLR4 create an optimal condition for the progression and metastasis of lung carcinoma." (PMID 37822929, 2023). "Thus, it is all the more surprising that the toll-like receptor (TLR) signaling pathway is upregulated in brain metastasis of lung-cancer patients and that TLR4 is expressed in microglia during colonization of the brain in a lung-cancer model." (PMID 36224342, 2022).